IFNG (interferon gamma)
Diseases named in the same sentence as IFNG in open-access papers (continued):
Sharing a sentence is not in itself a finding about the gene and the disease.
tumor (continued). "Thus, for activating anti-tumor T cell responses, the combination of IFNγ, R848, Hiltonol©, and LPS displayed the most promising cytokine profile." (PMID 28601925, 2017). "Likewise, studies have shown that the combination of the T-helper cell cytokines, IFNγ and TNFα, or genotoxic drugs induces tumor cell senescence and involves the JAK/STAT pathway." (PMID 29176033, 2017). "Functionally, intratumoral NK cells displayed impairments in the ability to both degranulate and produce IFNγ in response to classical NK cell targets, and they may rather acquire a proangiogenic phenotype due to the tumor microenvironment (TM)." (PMID 28348567, 2017). "NK cell activities for IFNγ production could be used as a supportive non-invasive tumor marker for GC diagnosis." (PMID 29050291, 2017). "Next, we wanted to determine whether there was a correlation between changes in ligand expression after IFNγ treatment and changes in NK cell-mediated tumor lysis." (PMID 28428785, 2017). "Of the 28/78 patients with a PD-L1+ biopsy, 15 showed evidence of TIMC, suggesting that environmental factors, such as IFNγ produced by activated T cells, could be responsible for PD-L1 expression by the tumor cells." (PMID 28199980, 2017). "Taken together, these studies indicate that apigenin may be able to trigger the production of IFNγ through tumor and immune cells." (PMID 28526810, 2017). "Moreover, gefitinib-mediated inhibition of EGFR destabilized PD-L1 surface expression in a GSK3β dependent fashion and enhanced tumor specific T cell immunity measured by CD8+ T cell IFNγ and granzyme B production." (PMID 28611673, 2017). "Activation of cytotoxic T lymphocytes could induce tumour killing by released cytokines, such as tumour necrosis factor-alpha and interferon-gamma." (PMID 28835713, 2017). "There are conflict results regarding the role of IFNγ in tumour progression." (PMID 29156701, 2017). "In mice bearing human tumors, galectin-3 reduces IFNγ diffusion through the tumor matrix." (PMID 28986561, 2017). "In a mouse model of C57Bl/6 mice injected i.v. with huCD20+ tumor cells and treated with an anti-huCD20 antibody, we have shown that IFNγ-producing NK cells, costimulatory molecules-expressing mature DC, and IL-12 production are critical for mAb-induced vaccinal effect." (PMID 28855903, 2017). "Moreover, IL-12 and IFNγ production by NK cells enhanced the anti-tumor efficacy of trastuzumab in a model of murine colon adenocarcinoma." (PMID 28855903, 2017). "However, differential effects were observed in IFNγ, granzyme A and B and Fas ligand expression, crucial effector molecules for tumor immunosurveillance." (PMID 28029653, 2017). "Adding galectin antagonists also boosted IFNγ-induced CXCL10 production in tumor xenografts." (PMID 28986561, 2017). "Glycoprotein/galectin-3 lattices could therefore retain glycosylated soluble factors, such as cytokines and in particular IFNγ, limiting their diffusion inside the tumor." (PMID 28986561, 2017). "We determined whether tumor IFNγ treatment affected NK cell-mediated lysis for 22 pediatric cancer cell lines from the PPTP in vitro panel." (PMID 28428785, 2017). "However, interferon gamma pathway also leads to an adaptive increase in PD-L1 expression on the tumor cells resulting in escape of T cell cytotoxic effects." (PMID 29069824, 2017). "This negative regulatory loop may decrease the T cell and NK cell activity in tumor microenvironment, which in our case might be more evident in the case of cetuximab which induces both higher IFNγ secretion and PD-L1 expression by immune cells." (PMID 28674498, 2017). "This tumor-promoting function for IFNγ is supported by the upregulated IFNγ observed in our study." (PMID 29088818, 2017). "Importantly, IFNγ can be released upon treatment with galectin antagonists, resulting in more T cells locally retained at the tumor site and in a delayed tumor growth." (PMID 28986561, 2017).
tumor (continued). "The ADNKs from obese cases have a decreased production of intracellular IFNγ upon tumor challenge." (PMID 29163547, 2017). "Some basic researches on immunological biomarkers and microenvironments, e.g., studies of intratumoral lymphoid infiltrates with intratumoral PD-L1 expression and the interferon-gamma pathway in tumor tissue, show that these factors can predict the response to immune checkpoint inhibitors." (PMID 28086948, 2017). "As IFNG induces upregulation of HLA molecules in cell lines in vitro, IFNG produced by tumor-infiltrating leukocytes may have a similar effect in vivo in high-risk UM." (PMID 27764126, 2016). "In addition, the mRNA levels of effector molecules such as IFNγ and granzyme-B in the lungs were reduced after tumor injection (P <0.001)." (PMID 27036297, 2016). "Assuming that these data reflect the underlying biology, these results imply that new CD8+ T cell immigrants to the tumor have a higher level of IFNG mRNA in rHuAd5-hDCT compared to rHuAd5-hgp100 immunized animals and that IFNG mRNA expression is regulated dynamically by cognate TCR interactions." (PMID 28101055, 2016). "Finally, intra tumor TNFα and IFNγ level was significantly reduced in DDB1F/F, Alb-Cre+/−, IL6−/− mouse comparing to DDB1F/F, Alb-Cre+/− mouse." (PMID 27556180, 2016). "Although memory-like NK cells with enhanced IFNγ production can be generated by in vitro IL re-stimulation, they often loss their “effector” function after ACT, thereby displaying limited benefit in controlling tumor growth or improving survival." (PMID 27816971, 2016). "Consequently the concept has emerged that a T-lymphocyte/IFNγ inflamed tumor microenvironment carries positive predictive value for responses to immunotherapy." (PMID 26885372, 2016). "In addition, silencing of JAK1 in a variety of tumor cell types, or treatment of these cells with JAK inhibitors, induced increased secretion of IFNγ by co-cultured NK cells and enhanced susceptibility of the tumor cells to NK-mediated lysis." (PMID 27366948, 2016). "Given that whole tumour lysate potentially contains large number of epitopes for CD4+ and CD8+ T-lymphocyte priming, we further investigated whether CD3+ tumour-specific IFNγ-secreting lymphocytes were being elicited by antigen loaded-DCs by flow cytometry." (PMID 26795765, 2016). "Tumor-infiltrating lymphocytes such as natural killer and T helper type 1 are effective components against cancer growth and/or metastasis in several cancers via their production of interferon gamma." (PMID 27198767, 2016). "We hypothesized that poxvirus-based immunotherapy would drive antigen-specific T cells to the tumor, concomitant with IFNγ production, thus inducing PD-L1 expression in the tumor microenvironment." (PMID 26910562, 2016). "CD8+ T cells also secrete IFNγ which are known to be essential for tumor eradication." (PMID 27120805, 2016). "As functional TILs secreting IFNγ could potentially upregulate PDL-1 expression within the tumor microenvironment, levels of PD-L1 on tumors were assessed." (PMID 27825115, 2016). "Notably, TNFα, together with IFNγ, plays an important role in initiating the immune response by activating tumor-specific cytotoxic T cells." (PMID 27678372, 2016). "Finally, given the fact that endogenous T-cell-derived IFNγ and exogenous TLRa were both essential for tumor rejection in CY+TLRa-treated mice, we also examined the capacity of added IFNγ and/or CpG to modulate host leukocytes’ tumoricidal function in vitro." (PMID 27341020, 2016). "Human blood monocytes could be rendered similarly tumoricidal during in vitro activation with TLRa+IFNγ, underscoring the potential therapeutic relevance of these mouse tumor studies to cancer patients." (PMID 27341020, 2016). "Moreover, IFNγ production was increased and tumor infiltration by NK cells and T cells was reported." (PMID 26993326, 2016).
tumor (continued). "Splenocytes from tumor-bearing mice appear to have been unaffected by the treatment, with a possible marginal trend of the spleen toward being depleted from perforin/IFNγ-expressing T cells." (PMID 28003813, 2016). "While weekly CY+TLRa treatment predictably resulted in partial depletion of tumor-reactive IFNγ-secreting T-cells, such treatment also produced an even greater body wide progressive depletion of Tregs, especially intratumorally, where as early as c2d3 Foxp3+ T-cells were virtually undetectable." (PMID 27341020, 2016). "This new pipeline for treatment may not only act on the transcriptional and non-transcriptional anti-tumor activities, but can also be beneficial for the induction of anti-tumor inflammatory responses, Fas-mediated apoptosis and tumor-sensitivity to IFNγ." (PMID 27897991, 2016). "These subsets of immunogenic tumors (e.g., MSI-H CRC) attract TILs, which produce IFNγ that up-regulates PD-L1 on tumor cells and demonstrate characteristic of an inflamed phenotype, such as prominent tumor lymphocytic infiltrate and macrophages located at the invasive front of the tumor." (PMID 27895917, 2016). "Our first attempts on the construction and characterization of MUC1 CAR T cells using variable regions of five of the antibodies, showed that they could be activated by MUC1 peptide to produce IFNγ, and lyse tumor cells." (PMID 27545199, 2016). "In addition, in tumour-infiltrating lymphocyte profile analysis, the population of activated cytotoxic T cells (CD8 and interferon gamma (IFNγ) positive) in 4T1 3SA tumours was lower than that in 4T1 WT tumours." (PMID 27572267, 2016). "To determine whether the extent of PD-1/PD-L1 interactions is associated with the size of the surviving fraction following exposure to anti-cancer drugs we increased the expression of PD-L1 in tumor cells using IFNγ." (PMID 26859684, 2016). "Low dose of targeted IFNγ can produce significant tumor growth inhibition in different tumor types." (PMID 27342639, 2016). "However, the tumor environment can promote dysfunction of high avidity T cells with reduced IFNγ production and expression of CD107a." (PMID 27825115, 2016). "Importantly, treatment of pro-tumor TAMs with IFNγ or with augmentation of the NF-κB pathway has been shown to reverse TAM polarization and induce a pro-inflammatory phenotype." (PMID 28003813, 2016). "In order to further confirm that the cell-based vaccinations induced an IFNγ response from lymphoid cells derived from the REAR mice in response to M6 tumor cells, an ELISPOT assay was performed on splenocytes derived from two mice from each of the experimental cohorts." (PMID 27171183, 2016). "One possibility is that an increase in IFNG production may increase antigen presentation by tumor cells indirectly by inhibiting the action of myeloid-derived suppressor cells." (PMID 28101055, 2016). "Taken together, the data suggest that TCP-1/TNFα and TCP-1/IFNγ could increase the generation of T lymphocyte in the spleen and enhance the penetration of T lymphocytes into the tumor." (PMID 27342639, 2016). "In addition, mice that received combinational treatment and experienced complete tumor regression had increased splenic IFNγ production, and were capable of mounting a durable immune response that negated the growth of these TNBC cells when rechallenged." (PMID 27169467, 2016). "TLR activation provokes the infiltration of natural killer (NK) cells, cytotoxic T cells and type I T helper cells into the tumor, where they induce tumor cell lysis via secretion of e.g., perforin and IFN-γ (interferon gamma) which results in the release of type I IFNs (IFN-α, β)." (PMID 27941651, 2016). "Based on our results, other agents that induce IFNγ at the tumor site may also facilitate enhanced tumor recognition by T-lymphocytes that have been previously primed by DC to recognize IP generated epitopes." (PMID 26885372, 2016).
tumor (continued). "In addition, we assumed that the phenotype of tumor infiltrating lymphocytes is conserved, but models incorporating this assumption (V1 and V2) were unable to capture observed changes in IFNG gene expression." (PMID 28101055, 2016). "Moreover, inhibition of expression of JAK1 or STAT1 abrogated the ability of IFNγ to upregulate PD-L1 in the tumor cell, and reduced the ability of these cells to hamper NK-mediated immunotherapy." (PMID 27366948, 2016). "It was hypothesized that the induced robust infiltration of IFNγ-producing T cells into the tumor could provoke an adaptive immune evasive response by the tumor through the upregulation of PD-L1 expression." (PMID 26910562, 2016). "Otherwise, chemotherapy can induce IL-2 and IFNγ secretion to trigger immunogenic cell death, and increase the permeability of tumor cells to granzyme B, thereby rendering them to be susceptible to CTL-mediated lysis even if they do not express the antigen recognized by CTLs." (PMID 26459255, 2016). "Besides their direct cytotoxic effect, CIK cells secret interferon gamma that modulates the expression of adhesion molecules on tumor cells, and the altered expression pattern of adhesion molecule enhances apoptosis that is induced by cytotoxic effector cells." (PMID 26842696, 2016). "Moreover, it was previously shown that the TLR2-L Pam3CSK4 improved the IFNγ response of tumor-infiltrating lymphocytes (TILs) after specific stimulation and had a slight advantage over Poly(I:C) and LPS in these assays." (PMID 27564262, 2016). "This problem may be readily overcome with a further refinement; the addition of strategies that generate IFNγ in the tumor micro-environment and induce IP expression." (PMID 26885372, 2016). "In fact, several studies have shown that TNF-α, IL-1, IL-6 and interferon gamma (IFN-γ), released by both tumor cells and the host in response to the tumor may lead to activation of different pathways of intracellular protein degradation." (PMID 27330885, 2016). "The transient disconnect between IFNG signal and tumor response could occur in a number of different ways." (PMID 28101055, 2016). "In addition, culture of CD8+ T cells with MDSC resulted in an increased ACT anti-tumor efficacy, which correlated with a higher frequency of the transferred T cells and elevated IFNγ production." (PMID 27007050, 2016). "In the V1 and V2 models, we assumed that the phenotype of CD8+ T cells that enter the tumor in response to rHuAd5-hgp100 and to rHuAd5-hDCT are the same and remain constant in time, which implies that dynamic changes in IFNG should track changes in TCRa gene expression." (PMID 28101055, 2016). "Classically activated M1 macrophages induced by interferon γ (IFNγ) and lipopolysaccharides are considered anti-tumor macrophages due to the expression of inducible nitric oxide synthase and the secretion of cytotoxic reactive oxygen species and pro-inflammatory cytokines." (PMID 28536380, 2016). "The finding that IFNγ inhibits the secretion of CXCL8 in BCPAP cells prompted us to evaluate whether cell migration, a well characterized CXCL8 mediated tumor-promoting activity, was also affected by IFNγ treatment." (PMID 27555670, 2016). "Interestingly, CD8+ cells in the spleen of tumor bearing mice that received beDCs had higher production of IFNγ upon stimulation with phorbol myristate acetate (PMA) + ionomycin." (PMID 27223090, 2016). "While total tumor-associated CD8+ T cell percentages were similar between PBS- and hAAT-treated mice, tumor-infiltrating CD8+ T cells in hAAT-treated mice were found to express significantly greater levels of perforin and IFNγ." (PMID 28003813, 2016). "Thus, αTGF-β therapy further enhances the tumor-specific IFNγ production in CD8+ TILs in a GVAX therapy dependent manner." (PMID 26515728, 2015). "As an alternative, IFNγ could be delivered to tumor cells by active immune cells such as ex vivo expanded NK cells." (PMID 26452036, 2015).
tumor (continued). "Interestingly, however, angiogenesis promoted by IL-17 was reduced considerably when IFNγ+ cells were present in the tumour." (PMID 26101460, 2015). "Interestingly, A549 xenografts stably transfected with control shRNA showed increased tumor growth when treated with IFNγ alone compared to the A549 xenografts transfected with anti-IDO shRNA." (PMID 26579709, 2015). "The IDO2 protein was detected by Western blot in three IFNγ-incubated tumor cell lines." (PMID 25691885, 2015). "This was followed by infiltration and induction of IFNγ-producing CD8 (Tc1) cells to the tumor bed." (PMID 25699053, 2015). "Interestingly, in these long-term shift-workers, TNF-α and a cytokine involved in tumor regulation, interferon-gamma (IFN-γ), were also hypomethylated." (PMID 26252151, 2015). "In this current study it was demonstrated that placental endothelial cells that are interferon gamma primed potently inhibit tumor growth in 3 histologically distinct animal models, as well as suppress pulmonary metastasis subsequent to intravenous tumor administration." (PMID 25889119, 2015). "Our data show that tumor-infiltrating CD8+ T cells in HPV-positive tumor samples not only were more frequent but also had a higher capacity to produce IFNγ and IL-17 upon PMA and ionomycin stimulation compared to HPV-negative tumors, indicating a stronger immune response." (PMID 25949860, 2015). "This is particularly relevant for IFNγ, which has a therapeutic application in a wide variety of immunological, viral, and neoplastic diseases, and where high percentages, up to 100%, of patients suffer from general side effects such as headache, malaise, and fever." (PMID 26501061, 2015). "Part of the IDO1 expression by tumor cells might result from an ongoing immune response involving T lymphocytes producing IFNγ." (PMID 25691885, 2015). "Furthermore, the presence of M1 macrophages in a subgroup of patients suggest the local presence of IFNγ as this is required for the optimal polarization in the local tumor milieu." (PMID 26357849, 2015). "In supernatants of HPV-positive tumors upon PMA and ionomycin stimulation we detected higher levels of IL-10, IL-17, IL-21, TNFα and IFNγ compared to supernatants of HPV-negative tumor samples; however, only the levels of IL-17 showed statistically significant differences (p = 0.030)." (PMID 25949860, 2015). "Second, we evaluated whether the lymphocytes that grew out exhibited autologous tumor-reactive function, as defined by >100 pg/mL IFNγ release when stimulated with autologous tumor and at least two times the background of T cells cultured alone." (PMID 26500776, 2015). "Additionally, the IFNγ produced by activated lymphocytes at the tumor site induces the expression of immunomodulatory molecules that dampen the immune response and inhibit the function of antitumor CTL." (PMID 26161423, 2015). "Interestingly, A549 xenografts transfected with anti-IDO shRNA showed significant delay in tumor growth in the presence of IFNγ alone when compared to A549 xenografts capable of producing IDO in the presence of IFNγ." (PMID 26579709, 2015). "Consequently, this bortezomib-enhanced Notch-NFκB crosstalk improves anti-tumor cytolytic functions such as IFNγ production and expression of effector molecules by CD8+ T cells." (PMID 26431276, 2015). "Decrease of CD3+IFNγ+ T cells in the tumor microenvironment can be partially converted by BMSCs in vivo and this effect might be related to MDSCs." (PMID 25889932, 2015). "The unmatched characteristics of human γδT cells to have MHC unrestricted tumor directed cytotoxicity, release of copious amounts of IFNγ, and recognition of cancer cells through variety of mechanisms render them as potential candidate for cancer immunotherapy." (PMID 25699053, 2015). "On the contrary, macrophage- and mast cell-derived cytokines that may participate in anti-tumor response include IL-1, IL-2, IL-4, IL-10, and interferon gamma (IFN-γ)." (PMID 25474039, 2015).